GOLGA6L6 (golgin A6 family like 6 (gene/pseudogene))
Synonyms: FLJ36131
Tractability: No criterion of Open Targets' tractability assessment is met for any kind of drug.
Gene: Protein-coding gene on chromosome 15 (20,531,856 to 20,541,800, reverse strand). Ensembl gene ENSG00000277322.
Genetic constraint (gnomAD): Loss-of-function variants: 5 observed, 10.57 expected, observed/expected ratio (o/e) 0.47, 90% interval 0.25 to 1. The upper end of that interval is the gene's LOEUF score, 1, which puts it in group 4 of 6, group 1 being the genes least tolerant of losing a copy. Missense variants: 76 observed, 103.73 expected, observed/expected ratio (o/e) 0.73, 90% interval 0.61 to 0.89. Synonymous variants: 22 observed, 20.66 expected, observed/expected ratio (o/e) 1.06, 90% interval 0.76 to 1.52.
Homologues: Paralogues in human: GOLGA6L22 (94% identical), GOLGA6L24 (92% identical), GOLGA6L25 (92% identical), GOLGA6L1 (86% identical), GOLGA6L26 (85% identical), GOLGA6L2 (45% identical), GOLGA6L7 (41% identical), GOLGA6L4 (20% identical), GOLGA6L10 (19% identical), GOLGA6L9 (17% identical).
Diseases named in the same sentence as GOLGA6L6 in open-access papers:
GOLGA6L6 is named in the same sentence as 2 diseases in open-access papers, as found by Europe PMC text mining. Sharing a sentence is not in itself a finding about the gene and the disease.
GOLGA6L6 shares sentences with these, for which no sentence is quoted: B cell CLL (1 paper); lymphoma (1).